CALR (calreticulin)
Diseases named in the same sentence as CALR in open-access papers (continued):
Sharing a sentence is not in itself a finding about the gene and the disease.
glioblastoma (12 papers, 2012 to 2025). The most malignant astrocytic tumor (WHO grade IV). "The ferroptosis inducers Erastin (ERA) and Ogremorphin (OGM) significantly enhance the immunogenicity of glioblastoma cells by driving the release of key damage-associated molecular patterns (DAMPs), including ATP and calreticulin exposure." (PMID 40756273, 2025). "Spatial multiplex imaging of glioblastoma resected as a lobectomy in continuity with the adjacent infiltrating brain shows that CALR is markedly expressed throughout the TME." (PMID 38786045, 2024). "Altogether, these results indicate that intratumoral injection with Ad-CALR/MAGE-A3 suppressed the tumor growth of glioblastoma cells in vivo." (PMID 22293781, 2012). "In the present study, the tube formation assay showed that Ad-CALR/MAGE-A3 attenuated the angiogenic potential of glioblastoma cells." (PMID 22293781, 2012). "There is wide recognition that in glioblastoma, CALR expression is increased, with high radiation sensitivity." (PMID 22293781, 2012). "The effect of Ad-CALR/MAGE-A3 transfection on glioblastoma cell proliferation was determined by MTT assay." (PMID 22293781, 2012). "Consequently, the reduction of MMP2 and MMP9 by Ad-CALR/MAGE-A3 will attenuate the metastatic potency of glioblastoma cells." (PMID 22293781, 2012). "In order to evaluate the effect of Ad-CALR/MAGE-A3 on U87 glioblastoma cells, we over-expressed human CALR and MAGE-A3 in U87 cells via adenovirus-mediated gene transduction, ensuring that we used the appropriate number of PFUs (MOI = 100) to obtain high expression of CALR and MAGE-A3." (PMID 22293781, 2012). "Moreover, in the in vivo model of glioblastoma, intratumoral injection of Ad-CALR/MAGE-A3 suppressed tumor growth and angiogenesis." (PMID 22293781, 2012). "However, a definite conclusion that the expression of CALR with MAGE-A3 in glioblastoma affects tumor cell proliferation, apoptosis, and invasion processes has not been established." (PMID 22293781, 2012). "Relative to CD47, the expression of CALR may be more prevalent in glioblastoma." (PMID 38786045, 2024). "In addition, molecular mechanisms underlying the antitumor effects of Ad-CALR/MAGE-A3 are partially revealed, which could serve as a rationale for gene therapy in the treatment of glioblastoma." (PMID 22293781, 2012). "Therefore, Ad-CALR/MAGE-A3 may potentially be a useful tool for gene therapy of glioblastoma, and even other cancers." (PMID 22293781, 2012). "In this study, we constructed the recombinant adenoviral vector Ad-CALR/MAGE-A3 and evaluated its antitumor effects on glioblastoma in vitro and in vivo." (PMID 22293781, 2012). "In this study, CALR and MAGE-A3 genes were delivered to the glioblastoma cell line U87, using adenovirus (Ad-CALR/MAGE-A3)." (PMID 22293781, 2012). "In this study, we successfully used Ad-CALR/MAGE-A3 to express CALR and MAGE-A3 proteins in the glioblastoma cell line U87." (PMID 22293781, 2012). "In vivo, the effects of Ad-CALR/MAGE-A3 on tumor growth and angiogenesis of U87 glioblastoma xenografts in nude mice were investigated." (PMID 22293781, 2012). "In the current study, CALR and MAGE-A3 overexpression in glioblastoma cells suppressed the Erk1/2 MAPK and PI3K/Akt signal pathways, which are well recognized for mediating cell proliferation and apoptosis." (PMID 22293781, 2012). "In summary, our findings show for the first time that overexpression of CALR and MAGE-A3 in glioblastoma cells by Ad-CALR/MAGE-A3 transfection can inhibit tumor growth and invasion in vitro and in vivo." (PMID 22293781, 2012). "By facilitating the release of ATP and the surface exposure of calreticulin, ferroptosis inducers like Erastin, which targets Xc-, and Ogremorphin, which targets GPR68, provide a promising avenue for enhancing the efficacy of immunotherapies in glioblastoma." (PMID 40756273, 2025).
glioblastoma (continued). "Our previous work had demonstrated that Nano-DOX could stimulate glioblastoma cells to release DAMPs including HMGB1, adenosine triphosphate (ATP), heat shock protein 90 (HSP90), and calreticulin (CRT)." (PMID 34488792, 2021). "Both in vitro and in vivo experiments demonstrated that TNFAIP2 knockout increases surface expression of calreticulin (CALR), heat shock protein 70 (HSP70), and heat shock protein 90 (HSP90) in glioblastoma (GBM) cell lines, thereby inducing ICD." (PMID 39184045, 2024). "A large number of genes are significantly correlated with CALR detected in BRCA, THCA, esophageal carcinoma (ESCA), stomach adenocarcinoma (STAD), KIRC, and glioblastoma multiforme (GBM), indicating that CALR is closely related to the other genes in the genome of these types of cancers." (PMID 34910788, 2021).
non-small cell lung carcinoma (12 papers, 2015 to 2023). A group of at least three distinct histological types of lung cancer, including non-small cell squamous cell carcinoma, adenocarcinoma, and large cell carcinoma. "Calreticulin (CALR) is a characteristic antigen involved in immunogenic cell death in non-small-cell lung cancer (NSCLC)." (PMID 35074008, 2022). "In addition, the potential of calreticulin to serve as a predictive biomarker to predict the RT-induced ICD response was investigated in the non-small cell lung cancer (NSCLC) setting." (PMID 33920544, 2021). "Interestingly, the combination of CALR and disulfide isomerase (PDIA3) was found to be a potential prognostic biomarker for non-small-cell lung cancer, which coincides with our finding of the upregulation of PDIA4 in ADC and PDIA3 and PDIA4 in SCC tissues." (PMID 35512017, 2022). "The combination of CALR and PDIA3 has also been suggested as a possible prognostic biomarker for non-small-cell lung cancer, with PDIA6 modulating apoptosis and autophagy of non-small-cell lung cancer cells via the MAP4K1/JNK signalling pathway." (PMID 36291587, 2022).
prostate carcinoma (12 papers, 2014 to 2024). A carcinoma that arises from epithelial cells of the prostate gland. "Our study delineates the interplay between TMCO1 and CALR, elucidates their association with the pathological characteristics and prognostic indicators of prostate cancer, and lays a theoretical groundwork for the development of targeted therapeutic interventions." (PMID 39479348, 2024). "Finally, we proposed that EBR induced apoptosis in prostate cancer cells by causing ER stress related to CALR downregulation and Ca2+ release into the cytosol." (PMID 26353013, 2015). "This study further demonstrated the regulatory mechanism of TMCO1 and CALR in the metastasis of prostate cancer." (PMID 39479348, 2024). "The present study aimed to investigate the relationship between transmembrane and crimp-crimp domain 1 (TMCO1) and calreticulin (CALR) in the pathological characteristics of prostate cancer and the mechanism of action on prostate cancer metastasis." (PMID 39479348, 2024). "TMCO1 and CALR are overexpressed in prostate cancer and knockdown of TMCO1 significantly inhibited the invasion, migration and cell proliferation." (PMID 39479348, 2024). "The inhibition of TMCO1 expression can reverse the effect of CALR induction, providing a theoretical reference for revealing the metastasis mechanism of prostate cancer cells." (PMID 39479348, 2024). "In the study, it was discovered that CALR can regulate the invasion and migration of prostate cancer cells, and can regulate mitochondrial membrane potential, calcium ion level, and ER stress, and the expression of Vimentin." (PMID 39479348, 2024). "Knockdown of TMCO1 expression significantly inhibited the proliferation ability of prostatic cancer cells, Moreover, the knockdown also mitigated the proliferative impact induced by the CALR recombinant protein." (PMID 39479348, 2024). "In summary, our study delineates the multifaceted roles of TMCO1 and CALR in prostate cancer, underscoring the potential of modulating calcium signaling pathways as a novel therapeutic approach." (PMID 39479348, 2024). "The expression level of TMCO1 and CALR were significantly higher in prostate cancer samples than in normal samples." (PMID 39479348, 2024). "It was recorded that EBR treatment induces ER stress mainly by targeting calreticulin in prostate cancer cells." (PMID 37529796, 2022). "Here, we show that BA treatment increased GRP78 which inhibits cell migration and calreticulin which suppresses prostate cancer by inhibiting growth and metastasis." (PMID 27587023, 2017). "It is speculated that CALR may affect the metastasis of prostate cancer through calcium ion level and ER stress." (PMID 39479348, 2024). "The experimental outcomes demonstrated that the knockdown of TMCO1 could reverse the effect of CALR in inducing prostate cancer cell metastasis." (PMID 39479348, 2024). "Because CALR is a chaperone protein and because alterations in the CALR expression lead to the unfolded protein response and ER stress, we detected the interactions of CALR with other molecules to detect evidence of the UPR following EBR treatment in LNCaP prostate cancer cells." (PMID 26353013, 2015). "Therefore, we propose a hypothesis that TMCO1 and CALR influence ER calcium regulation and mediate prostate cancer cell metastasis." (PMID 39479348, 2024). "Knockout of TMCO1 can reverse the effect of CALR recombinant protein, elucidating the pivotal roles of TMCO1 and CALR in the regulation of prostate cancer metastasis through modulation of calcium homeostasis." (PMID 39479348, 2024). "At 10 Gy 223Ra, calreticulin expression increased 5.5-fold and 2.5-fold in LNCaP and PC3 prostate carcinoma cells, respectively, compared to untreated controls." (PMID 27893426, 2016).
prostate carcinoma (continued). "Further, CP1 induced ICD in both mouse and human prostate cancer cells in vitro, as determined by increased HMGB1, ATP, calreticulin, and CXCL10, and in tumor tissue in vivo, as determined by HMGB1 secretion and increased cell surface calreticulin." (PMID 29686284, 2018). "In conclusion, all data in this study suggest that EBR is an effective apoptotic agent through modulating the CALR expression profile and thus causing deficient Ca2+ buffering potential regardless of NHR expression in prostate cancer cells." (PMID 26353013, 2015). "EBR decreased the CALR and CALNX expression profiles time-dependently by causing caspase-dependent apoptotic cell death in both AR-expressing and AR-non-expressing prostate cancer cells." (PMID 26353013, 2015). "Immunohistochemistry analysis of prostate carcinomas 72 h post-irradiation showed increased expression of the immunoproteosome components LMP2 and LMP7, the peptide transporter TAP2, and the chaperones tapasin and calreticulin." (PMID 24480782, 2014). "Therefore, we suggest that EBR might act on a Ca2+ buffering mechanism via altering CALR expression regardless of NHR status in prostate cancer cells." (PMID 26353013, 2015).
hepatocellular carcinoma (11 papers, 2005 to 2026). A malignant tumor that arises from hepatocytes. "Mechanistically, H3K4 methylation drove TESC expression in hepatoma cells, facilitating cytosolic Ca2+ buffering and attenuating endoplasmic reticulum (ER) stress-induced calreticulin (CALR) plasma membrane exposure, an essential "eat-me" signal." (PMID 41926218, 2026). "In a previous study we have demonstrated that a particular form of calreticulin elicits a humoral response in hepatocellular carcinoma, with the reactive epitope occurring in a truncated form (CRT32, which includes the C-terminal portion), whereas the intact protein did not elicit reactivity." (PMID 18769604, 2006). "Similar anti-angiogenic effects have been reported with recombinant T. cruzi calreticulin in the murine mammary TA3 MTXR tumour model and Sja-miR-61 in a murine hepatic carcinoma model." (PMID 40247360, 2025). "CALR as a Ca2+-binding chaperone located in ER lumen is responsible for modulating proper folding of neo-synthesized glycoproteins and for calcium retention; however, MANF as a negative regulator of unfolded protein response could alleviate hepatocellular carcinoma by suppressing EMT." (PMID 36639674, 2023).
leukocytosis (11 papers, 2014 to 2025). "ExT clustered with CALR (type-2 more than type-1) and TN and leukocytosis with JAK2 mutation (p < 0.01)." (PMID 38238303, 2024). "The CALR-mutated patients had a significantly lower cumulative incidence of developing leukocytosis compared to JAK2 mutant patients (p = 0.004)." (PMID 37444441, 2023). "Leukocytosis developed by KI mice, especially in the homozygous setting, was unexpected from CALR-mutated patient studies and was due to a general increase in the different white blood cell (WBC) populations." (PMID 32985500, 2020). "In contrast to CALR-mutated patients who show little leukocytosis compared to JAK2V617F NMPs, we observed that del52 and, to a slightly lesser extent, ins5 KI mice develop leukocytosis that is dependent on zygosity." (PMID 32985500, 2020). "Patients with CALR mutations were also less likely to be anemic, require transfusions, or display leukocytosis." (PMID 25386351, 2014). "ExT clustered with CALR (type-2 more than type-1), TN and MPL, and leukocytosis with JAK2 mutation (p < 0.001)." (PMID 38238287, 2024). "CALR mutations in PMF were correlated with patients who were younger, less likely to be anemic and require transfusions, and had a higher platelet count and a lower incidence of leukocytosis." (PMID 37444441, 2023).
myelodysplastic syndrome (11 papers, 2014 to 2025). A clonal hematopoietic disorder characterized by dysplasia and ineffective hematopoiesis in one or more of the hematopoietic cell lines. "In other study, CALR mutations have also been detected in patients with myelodysplastic syndrome (8.3%; n=120), chronic myelomonocytic leukemia (3%; n=33), and atypical chronic myelogenous leukemia (CML) (3.4%; n=29)." (PMID 27486987, 2016). "Magrolimab has consequently been combined with calreticulin-inducing azacytidine in a phase 1b trial including untreated AML patients unfit for chemotherapy and patients with intermediate to very high-risk myelodysplastic syndrome (MDS)." (PMID 34579739, 2021).
myeloma (11 papers, 2019 to 2025). "A study in multiple myeloma showed that high CALR expression was associated with an increased PD-L1 level." (PMID 37762557, 2023). "In fact, recent studies reveal that bortezomib can induce the display of CALR on the surface of dying myeloma cells, the uptake of tumor cells by DCs, and the stimulation of a myeloma-specific immune response." (PMID 40565309, 2025). "In this study, we also selected calreticulin (CRT, a multifunctional protein predominantly located in endoplasmic reticulum) as an immune adjuvant to amplify the specific anti-myeloma immune response elicited by the CS1-DNA vaccine." (PMID 33330069, 2020). "Evidence also showed that the deletion of the GABARAP protein diminished the surface exposure of CALR during immunogenic cell death (ICD), subsequently reduced phagocytosis, disrupted the Golgi apparatus, and interrupted the autophagy machinery in multiple myeloma cells." (PMID 40650127, 2025).
cervical carcinoma (10 papers, 2009 to 2025). A carcinoma arising from either the exocervical squamous epithelium or the endocervical glandular epithelium. "Of the 17 downregulated proteins, 6 different proteins showed low expression in both vaginal and cervical carcinoma compared with normal vaginal tissue (calreticulin, tropomyosin 2 beta, vimentin, gelsolin, vinculin and filamin)." (PMID 19367286, 2009). "CD47 and calreticulin levels were analysed using qRT-PCR and flow cytometry to examine whether phagocytosis of the human cervical cancer cells by THP-1 macrophages is mediated by phagocytic molecules." (PMID 34093795, 2021). "Furthermore, the addition of cisplatin to an immunotherapy vaccine comprised of calreticulin and papillomavirus 16 E7 antigens for the treatment of cervical cancer enhances CD8+ T cell responses." (PMID 30906773, 2019). "Liquiritin exerts immunogenic cell death (ICD) effects on human cervical cancer by inducing HMGB1 release, ATP secretion, and calreticulin exposure through ER stress." (PMID 40002335, 2025). "Among the multiple proteins secreted by cervical cancer cells, four upregulated proteins were identified: nucleobindin-1 (NUCB1), carboxypeptidase E (CPE), calreticulin (CALR), and heat-shock protein beta-1 (HSPB1)." (PMID 36992411, 2023).